ABHD6 (abhydrolase domain containing 6, acylglycerol lipase)
Diseases named in the same sentence as ABHD6 in open-access papers (continued):
Sharing a sentence is not in itself a finding about the gene and the disease.
uveal melanoma (1 paper, 2022). A melanoma derived from melanocytes of the uveal tract. "Moreover, ABHD6 expression in early metastatic UM was significantly downregulated compared to primary non-metastatic uveal melanoma, which corroborates our study findings within SF3B1mut UM." (PMID 35159112, 2022).
cancer (7 papers, 2019 to 2023). A tumor composed of atypical neoplastic, often pleomorphic cells that invade other tissues. "It has been reported that expression of ABHD6 is related to the pathogenesis of Epstein-Barr virus (EBV)-associated malignant tumors, such as Hodgkin’s lymphoma, endemic Burkitt’s lymphoma, and posttransplant lymphoma." (PMID 34925039, 2021). "Interestingly, ABHD6 has been associated with cancer growth and metastasis in different tumor types." (PMID 36693836, 2023). "Overall, it is very important to confirm whether ABHD6 acts as a diagnostic marker and therapeutic target for malignant tumors." (PMID 34925039, 2021). "Comparative ABPP with serine hydrolase probe FP-TAMRA revealed that the activity of MAGL was found in most of the cells, but varied in different cancer cell lines, whereas the activity of ABHD6 was only found in A431 and B16-F10." (PMID 36105202, 2022). "PDAC is one of the most lethal cancers with a high metastasis rate, and pharmacological and genetic inhibition of ABHD6 confirms reduced PADC cell proliferation in vitro and tumor metastasis in vivo." (PMID 34925039, 2021). "Deletion or inhibition of ABHD6 activity has been shown to be beneficial in certain cancers." (PMID 31349646, 2019). "Finally, ABHD6 was shown to affect cancer cell lipid metabolism and tumor malignancy." (PMID 36005632, 2022). "Firstly, we evaluated the expression levels of endogenous MAGL, ABHD6, and ABHD12 in the cancer cells by western blot analysis." (PMID 36105202, 2022). "In summary, we are of the opinion that CPT1C in cancer cells behaves as a nutrient sensor that facilitates tumor progression and metabolic adaptation to environmental stressors through regulation of SAC1, protrudin, ABHD6, and possibly other proteins." (PMID 36693836, 2023). "The authors observed substantial upregulation of ABHD6 in tumor tissues and proposed that lack of ABHD6 leads to the accumulation of MAG, promoting cancer aggressiveness." (PMID 36005632, 2022).
tumor (7 papers, 2012 to 2023). "Subsequent studies suggested that ABHD6 is highly abundant in Ewing family tumor cell lines and might be an interesting new diagnostic or therapeutic target." (PMID 36005632, 2022). "Overall, these studies identify ABHD6 as an interesting target for the development of anti-metastatic and anti-tumor therapies." (PMID 36005632, 2022). "ABHD6 correlates significantly with the tumor lymph node metastasis stage, which indicates a poor overall survival in NSCLC patients." (PMID 34925039, 2021). "Recently, ABHD6 has been reported to be the primary MG lipase in NSCLC and blockade of ABHD6 significantly reduced the migration, invasion, and in vivo tumor growth of NSCLC." (PMID 33413672, 2021). "Even before its biochemical characterization, ABHD6 was found to be differentially expressed in tumor cell lines, ranging from very high expression in U2OS (bone), PC-3 (prostate), and Jurkat (leukocyte) cells, to absent expression in Hela (cervical) and U251 (brain) cells." (PMID 36005632, 2022). "Furthermore, ABHD6 inhibition blunted metastatic seeding and tumor growth in mice." (PMID 36005632, 2022). "Our attempts to validate the differential expression of ABHD6 and CSRNP1 transcripts with IHC and RT-qPCR was hampered due to the scarcity of N2-stored tumor tissue." (PMID 35159112, 2022). "Moreover, increased expression of ABHD6 is found in U2OS (bone), Jurkat (leukocyte), PC-3 (prostate) and other tumor cell lines." (PMID 34925039, 2021). "Notably, ABHD6 silencing reduces the migration and invasion of NSCLC cells in vitro as well as metastasis and tumor growth in vivo." (PMID 34925039, 2021).
metabolic disease (3 papers, 2019 to 2021). A congenital disorder (due to inherited enzyme abnormality) or acquired (due to failure of a metabolically important organ) disorder resulting from an abnormal metabolic process. "Specifically, the first study that targeted ABHD6 in peripheral tissues through antisense oligonucleotides demonstrated that ABHD6 is involved in metabolic disorders induced by HFD feeding." (PMID 34718828, 2021). "In conclusion, our results suggest that common metabolic diseases and ABHD6 affect BMP metabolism in mice and humans." (PMID 30894461, 2019). "Here, we demonstrate that common metabolic disorders and the intracellular BMP hydrolase α/β-hydrolase domain-containing 6 (ABHD6) affect BMP metabolism in mice and humans." (PMID 30894461, 2019).
Neurological Diseases (2 papers, 2021). "Compared with inhibition of MAGL, also a potential target for inflammatory disease, ABHD6 inhibition has fewer side effects (detailed in subsection 5, ABHD6 and Neurological Diseases)." (PMID 34925039, 2021). "MAGL and ABHD6 inhibitors have shown promise as pain therapeutics and in treating neurological disorders, respectively." (PMID 34749819, 2021). "In this review, the latest research progress on ABHD6 for the treatment of nervous system diseases is reviewed in terms of its molecular structure, expression, and mechanism of action in the CNS." (PMID 34925039, 2021). "Overview of reported neurological disease treatments targeting ABHD6." (PMID 34925039, 2021). "This review summarizes the molecular mechanisms of action and biological functions of ABHD6, particularly its mechanism of action in the pathogenesis of neurological diseases, and provides a theoretical basis for new pharmacological interventions via targeting of ABHD6." (PMID 34925039, 2021). "ABHD6 plays a potential regulatory role in the neuroinflammatory pathway and autoimmunity and is expected to become a new target for intervention in nervous system diseases." (PMID 34925039, 2021). "Therefore, inhibition of ABHD6 may help in preventing CB1R desensitization, making ABHD6 a promising new pharmacological target for the treatment of neurological diseases." (PMID 34925039, 2021).
ABHD6 also shares sentences with these, for which no sentence is quoted: diabetes (4 papers); brain injury (3); Alzheimer disease (2); type 2 diabetes (2); amyotrophic lateral sclerosis (1); Anxiety (1); bone cancer (1); Burkitt lymphoma (1); hearing loss (1); hepatocellular carcinoma (1); ischemia (1); leukemia (1); mental illness (1); metastatic melanoma (1); neuropathy (1); pancreatic ductal adenocarcinoma (1); polyneuropathy (1); prostate carcinoma (1); retinitis pigmentosa (1); schizophrenia (1).